FBN1 (fibrillin 1)
Diseases named in the same sentence as FBN1 in open-access papers (continued):
Sharing a sentence is not in itself a finding about the gene and the disease.
ovarian carcinoma (continued). "In ovarian cancer cells, overexpression of Zeb1 induced mesenchymal markers TSHZ1 and FBN1, thus promoting EMT." (PMID 26356073, 2015). "However, the fibrillin-1 gene (FBN1) has been found to be upregulated in various cancers, including gastric cancer, osteosarcoma, and ovarian cancer." (PMID 39273393, 2024). "FBN1 was significantly over-expressed in HOSEpiC cells compared to all studied ovarian cancer cell lines, whereas no apparent change in the expression of OR4M1 was noted across all five cell lines." (PMID 34386072, 2021). "Overexpression of Snail in ovarian cancer cells induced mesenchymal markers, such as tea-shirt zinc finger homeobox (TSHZ1), collagen type Vα, and fibrillin-1 (FBN-1), while suppressing E-cadherin, myosin-5C, keratin-18, keratin-8, annexin-A3, and suppressor of tumorigenicity 14 (ST14)." (PMID 26356073, 2015). "Studies show that FBN1 regulates glycolysis and angiogenesis through activation of the vascular endothelial growth factor receptor 2 (VEGFR-2)/STAT2 pathway, decreases the sensitivity of ovarian cancer to cisplatin and promotes chemoresistance in ovarian cancer." (PMID 38269088, 2023). "Therefore, IGFBP1, FBN1, SERPINA1 not only have complex interactions with WT1, but also may jointly regulate the migration and invasion of ovarian cancer cells." (PMID 34692659, 2021). "Moreover, the cell growth of papillary thyroid carcinoma is inhibited by miR-486-5p by targeting fibrillin-1, and estrogen receptor-mediated miR-486-5p could regulate the expression of OLFM4 in ovarian cancer." (PMID 32359364, 2020). "Furthermore, miR-486 might inhibit cell growth of papillary thyroid carcinoma by targeting fibrillin-1 and estrogen receptor-mediated miR-486 could regulate expression of OLFM4 in ovarian cancer." (PMID 29568407, 2018). "Moreover, the samples of ovarian cancer where RT-qPCR was performed were all stage III/IV, as such we do not have the data to compare mRNA expression of FBN1 and OR4M1 in early stages of ovarian cancer." (PMID 34386072, 2021).
Weill-Marchesani syndrome (27 papers, 2008 to 2025). Weill-Marchesani syndrome (WMS) is a rare condition characterized by short stature, brachydactyly, joint stiffness, and characteristic eye abnormalities including microspherophakia, ectopia of the lens, severe myopia, and glaucoma. "This variant in FBN1 gene is reported to be associated with Weill Marchesani syndrome (clinical manifestations are short limb deformity, secondary glaucoma, short stature, etc.)." (PMID 37875969, 2023). "ADAMTS10 promotes fibrillin-1 microfibril assembly, consistent with the observation that recessive ADAMTS10 mutations and dominantly inherited FBN1 mutations each lead to Weill-Marchesani syndrome." (PMID 35503090, 2022). "The individual with a damaging mosaic variants in FBN1, which is associated with several genetic syndromes, had features consistent with Weill-Marchesani syndrome such as brachycephaly, mitral valve stenosis, short stature, and midface hypoplasia." (PMID 32349777, 2020). "ADAMTSL2 binds to fibrillin-1 and the N-terminal binding site encompasses a fibrillin-1 mutation which results in Weill Marchesani Syndrome (WMS)." (PMID 31226403, 2019). "Certain FBN1 mutations cause syndromes with musculoskeletal features that are the opposite of MFS (short stature acromelic dysplasias such as Weill-Marchesani syndrome (WMS) and geleophysic dysplasia or acromicric dysplasia)." (PMID 26114882, 2015). "Mutations in ADAMTS10, ADAMTS17 and in fibrillin 1 (FBN1) have been associated with a Weill-Marchesani syndrome (WMS) (OMIM 277600)." (PMID 25372548, 2014). "However, it is mutated in Weill-Marchesani syndrome, a connective tissue disorder linked to defects in the processing of fibrillin-1 and -2 that perturb the architecture of microfibrils and their ability to store latent TGF-β and several BMPs25–27." (PMID 40064965, 2025). "A novel mutation in fibrillin-1 demonstrates that modulation of the fibrillin microfibril scaffold can influence tissue microenvironments and result in the clinical features of Weill-Marchesani syndrome (WMS), including thick skin, short stature, and brachydactyly." (PMID 22242013, 2012). "Mutations in the FBN1 gene that cause skeletal dysplasias include acromicric dysplasia (AD), geleophysic dysplasia (GD), and Weill-Marchesani syndrome (WMS)." (PMID 40740820, 2025). "ADAMTS10 mutations cause Weill-Marchesani syndrome (WMS), implicating it in fibrillin microfibril biology since some fibrillin-1 mutations also cause WMS." (PMID 27779234, 2016). "Here we show that a novel FBN1 mutation in a family with Weill-Marchesani syndrome (WMS) causes thick skin, short stature, and brachydactyly when replicated in mice." (PMID 22242013, 2012). "In contrast, two fibrillin-1 mutations cause autosomal dominant Weill-Marchesani syndrome (WMS), which is characterized by short stature, thick skin, stiff joints and ocular problems." (PMID 23133647, 2012). "Studies have observed that a catalytically inactive ADAMTS17 interferes with fibrillin-1 secretion, resulting in elastic fiber abnormalities and intracellular collagen accumulation in fibroblasts from patients with Weill-Marchesani syndrome." (PMID 39575453, 2024). "Recessive ADAMTS10 mutations lead to an acromelic dysplasia, Weill-Marchesani syndrome 1 (WMS1), whereas dominant FBN1 mutations cause a phenotypically similar disorder, WMS2, suggesting a functional relationship between ADAMTS10 and fibrillin-1." (PMID 35503090, 2022). "Mutations in the FBN1 gene not only cause MFS with tall stature and joint laxity, but also cause the opposite manifestation, which is mainly seen in Weill-Marchesani syndrome (WMS), Geleophysic dysplasia (GD) and Acromelic dysplasias (AD)." (PMID 38269088, 2023). "Studies of Weill-Marchesani syndrome strongly suggest ADAMTS10 (GeneID: 81794) regulates TGF βsignaling through its interactions with the ECM component, fibrillin-1 (GeneID: 2200)." (PMID 18454205, 2008).
Weill-Marchesani syndrome (continued). "Alterations in FBN1 gene also lead to MASS (mitral valve, myopia, aorta, skin and skeletal condition) phenotype, Marfanoid-progeroid-lipodystrophy, Acromic dysplasia, Stiff skin syndrome (SSS), Geleoplastic dysplasia, Weill-Marchesani syndrome (WMS), which are not related to MFS." (PMID 38269088, 2023).
aneurysm (26 papers, 2007 to 2025). Bulging or ballooning in an area of an artery secondary to arterial wall weakening. "In the case shown here, a MFS patient with the FBN1 c.7399C>T (p.Q2467X) mutation developed additional aneurysms in the aortic arch following repair of the aortic root and ascending aorta." (PMID 41040364, 2025). "In a previous case report, an MFS patient with an FBN1 mutation developed an aneurysm and was detected with abnormal retinal vascular morphology in both eyes." (PMID 36866161, 2023). "Heterozygous nonsense, missense, and complete deletions of FBN1, as well as mutations affecting splicing, cause hereditary aneurysms associated with MFS." (PMID 33514025, 2021). "Our findings confirm the possibility of the occurrence of internal mammary artery aneurysms in patients with FBN1 mutation and we believe that monitoring these aneurysms with blood pressure management can be a suitable option in selected cases." (PMID 34222386, 2021). "This system allows us to study the lineage-specific role in aneurysm formation in vitro using SMCs from clinical patients with FBN1 mutations, providing a platform for novel molecular pathway discovery and potentially drug/therapeutic testing." (PMID 33230159, 2020). "Additional studies of mice hypomorphic for fibrillin-1 or heterozygous for a structural fibrillin-1 mutation (Fbn1mgR/mgR mice and Fbn1C1041G/+ mice, respectively) correlated aneurysm progression with improper stimulation of angiotensin II (AngII) type 1 receptor (At1r) signaling." (PMID 35053276, 2022). "In conclusion, we report here three individuals with MFS and compound heterozygous mutations in FBN1, all of whom had severe aneurysmic disease, suggesting a gene dose effect of FBN1 mutations may contribute to a more severe phenotype." (PMID 31950671, 2020). "Additionally, in the aneurysm group, patients with a FBN1 truncating or splicing mutation took a prophylactic surgery at a younger age (25.6y vs. 33.4y) than those with a missense mutation." (PMID 27611364, 2016). "Fbn1123 codes for fibrillin-1; deletions in this gene are implicated in aneurysm." (PMID 22970191, 2012). "Angiotensin II infusion into fibrillin-1 C1041G/+ mice promoted development of prominent aortic pathologies, including enhanced aneurysm and rupture in both the thoracic and abdominal regions." (PMID 41394635, 2025). "Angiotensin II infusion into fibrillin-1 C1041G/+ mice promoted development of pronounced aneurysms at the aortic branches of the celiac and superior mesenteric arteries." (PMID 41394635, 2025). "One side of research has demonstrated a pathogenic role for TGF-β, with dysregulation of TGF-β signaling due to variants in fibrillin-1 (FBN1) being contributory to CMN of the medial layer in the aortic wall, leading to aneurysm development." (PMID 38892036, 2024). "The functional impairment of the aorta as imposed by the Fbn1 variant does not therefore reflect aneurysm progression." (PMID 38545339, 2024). "Perhaps a different environment in which mild exercise is encouraged, could also reduce the debilitating effects of low levels of fibrillin-1, and decrease the incidence of aneurysm." (PMID 17311093, 2007). "However, the mechanism whereby FBN1 truncating or splicing mutations exert their effect on aneurysm progression and severity is not clear, which deserves our further investigation." (PMID 27611364, 2016). "The detection of FBN1 point mutations in patients with BAV with aortic dilatation/aneurysm but without MFS adds to the striking clinical heterogeneity of type I fibrillinopathies to include a small number of patients bearing the most common congenital heart disease." (PMID 24564502, 2014). "During aneurysm progression, GzmB cleaves many extracellular matrix proteins including DCN and fibrillin-1 both of which play pivotal roles in maintaining vessel wall stability." (PMID 29158532, 2017).
aneurysm (continued). "We found five FBN1 VUS, two in familial and three in sporadic patients including three VUS previously reported in aneurysm patients in HGMD." (PMID 26017485, 2015). "One proposed mechanism involved in MFS aorto-pathy is the function of FBN1 as a regulator of TGF-β (transforming growth factor β) bioavailability, whereby defective FBN1 production leads to heightened TGF-β signaling and eventual aortic dilatation and aneurysms in mice." (PMID 31315432, 2019). "Because fibrillin-1 is the main component of microfibrils, we reasoned that microfibril defects in Ltbp2/4S DKO mice could cause aneurysms, which turned out not to be the case." (PMID 28252045, 2017).
stiff skin syndrome (23 papers, 2010 to 2025). A rare syndrome characterized by hard, thick skin, usually on the entire body. "Mutations in the region near the RGD binding site in FBN1 result in a state called stiff skin syndrome (SSS), and this domain is associated with a pathological state which is characterized by the excessive deposition of microfibers and fibrosis in the skin." (PMID 38269088, 2023). "This is a report about acromicric dysplasia with stiff skin syndrome‐like severe cutaneous presentation caused by a single hotspot mutation, further revealing the gene pleiotropy of FBN1." (PMID 32406602, 2020). "Transgenic mice expressing a mutant FBN1 gene, which encodes a mutated form of fibrillin-1 responsible for stiff skin syndrome, exhibit features of SSc with aggressive skin fibrosis." (PMID 25077037, 2014). "More recently, mutations in FBN1 were found in Stiff Skin Syndrome (SSKS, OMIM #184900), a rare disorder characterized by hard, thick skin and joint contractures." (PMID 22242013, 2012). "In this respect, it resembles human stiff skin syndrome and the Tight skin mouse, each of which is caused by gene defects affecting fibrillin-1, a major component of tissue microfibrils." (PMID 20862248, 2010). "By contrast, there is a very strong correlation between mutations affecting a specific domain of fibrillin-1 and the unique phenotype of stiff skin syndrome (SSS; OMIM 184900)." (PMID 21126338, 2010). "This study reports about the coexistence of stiff skin syndrome‐like severe cutaneous presentation and acromicric dysplasia in a single patient caused by a single hotspot mutation, further revealing the gene pleiotropy of FBN1." (PMID 32406602, 2020). "For Stiff Skin Syndrome, though there are limited number of mutations, LSL-FBN1 provided a clear difference between mutant and wildtype FBN1 sequences." (PMID 39864627, 2025). "We applied LSL to FBN1 to investigate the ability to discriminate pathological from benign mutants related to Marfan’s disease and Stiff Skin Syndrome." (PMID 39864627, 2025). "In the stiff skin syndrome (SSS; MIM#184900), a rare, autosomal dominant condition of congenital scleroderma (thickened skin) associated with short stature, domain-specific FBN1 mutations have been identified." (PMID 22801769, 2013). "Recently, stiff skin syndrome (SSS) and a group of syndromes known collectively as the acromelic dysplasias, which typically result in short stature, skin thickening and joint stiffness, have been linked to FBN1 mutations that affect specific domains of the fibrillin-1 protein." (PMID 25979247, 2015). "On the other hand, mutations located around the integrin-binding site of fibrillin-1 perturb cell matrix interactions, architectural matrix assembly and extracellular distribution of latent TGF-β complexes, and lead to the highly restricted fibrotic phenotype of Stiff Skin syndrome." (PMID 21126338, 2010). "Furthermore, mice lacking fibrillin-1 (Fbn1), which spontaneously develop a stiff skin syndrome that recapitulates the skin fibrosis observed in SSc patients, show a high infiltration of pDCs in the affected skin." (PMID 30083163, 2018).
aortic root dilatation (21 papers, 2013 to 2025). "Diagnosis is made by the revised criteria, Ghent nosology, which considers a family history of aortic root dilatation, patient history of dilatation, or an FBN1 mutation that was previously associated with aortic root dilatation." (PMID 40416127, 2025). "In a Korean MFS cohort, up to 89.8% of patients who had FBN1 mutationsin genetic analysis developed aortic root aneurysm/dissection, and 62% of patients underwent some type of cardiovascular surgery." (PMID 29416815, 2018). "We detected three FBN1 mutations in two patients (aged 24 and 25 years) displaying aortic root aneurysm ≥50 mm and moderate aortic regurgitation." (PMID 24564502, 2014). "•Ectopia lentis AND FBN1 mutation with known aortic root dilatation." (PMID 40123664, 2025). "Moreover, our analysis focused only on the main diagnostic criteria such as FBN1 positivity, aortic root dilatation and lens dislocation and revealed correlations of miRNA expression to cardiovascular features such as aortic root dilatation and mitral valve prolapse." (PMID 29530068, 2018). "Rare variants of FBN1, encoding an extracellular glycoprotein (fibrillin-1), have been found in BAV and aortic root aneurysms." (PMID 40566523, 2025). "MFS (FBN1 gene defect) patients have normal or tall stature, dolichostenomelia, pectus excavatum or carinatum, scoliosis, aortic root dilatation, mitral or tricuspid valve regurgitation, skin striae, and pes planus." (PMID 39421111, 2024). "Rare variants of FBN1 encoding an extracellular glycoprotein (fibrillin-1) have been found in NS-BAV and aortic root aneurysms." (PMID 39589938, 2024). "Mutations in the fibrillin-1 (FBN1) gene is associated with increased aortic stiffness, elevated PP and aortic root dilatation." (PMID 32303188, 2020). "Despite systemic effects of FBN1 mutations, patients with MFS typically develop aortic root aneurysms." (PMID 33230159, 2020). "Furthermore, this study is limited to evaluating a single Fbn1 mutation associated with MFS, specifically the mutation observed in patients who present with aortic root aneurysm." (PMID 39959812, 2024). "If we postulate a genetic background to BAV aortopathy, it would be reasonable to assume that FBN1 variants would dominate the genetic cause of aortic root aneurysm, as common FBN1 variants have been associated with non-syndromic bicuspid aortic aneurysm, independent to the position of the aneurysm." (PMID 28993736, 2017).
arachnodactyly (20 papers, 2010 to 2025). "Heterozygous mutations in fibrillin-1 or fibrillin-2 cause two clinically related disorders of the connective tissue, MFS (OMIM 154700) and congenital contractural arachnodactyly (CCA: OMIM 121050) respectively." (PMID 21126338, 2010). "The gene FBN2 has high similarity to FBN1; as a result, pathogenic variants in FBN2 have been reported to cause a phenotypically related disorder termed congenital contractual arachnodactyly (CCA) (MIM:121050), which also presents with Marfanoid body habitus and arachnodactyly." (PMID 38791509, 2024).
Loeys-Dietz syndrome (20 papers, 2015 to 2026). Loeys-Dietz syndrome is a rare genetic connective tissue disorder characterized by a broad spectrum of craniofacial, vascular and skeletal manifestations with four genetic subtypes described forming a clinical continuum. "Conceptual cores were anchored in syndromic and heritable thoracic aortic disease genetics (e.g., Marfan and Loeys-Dietz syndromes; FBN1 and TGF-beta signaling), increasingly linked to diagnosis, variant interpretation, risk stratification, guidelines, and management." (PMID 42199299, 2026). "These included FBN1, ADAMTS2 and TGFB2 which associate with connective tissue disorders (Marfan, Ehlers-Danlos and Loeys-Dietz syndromes), and the LUM-DCN-KERA gene complex involved in myopia, corneal dystrophies and cornea plana." (PMID 29760442, 2018). "Among these, Loeys-Dietz syndrome (MIM # 609,192) shows mutations in other genes which are involved in the same pathway of FBN1 and include TGFBR1 (MIM * 190,181), TGFBR2 (MIM * 190,182), SMAD3 (MIM * 603,109), TGFB2 (MIM * 190,220), TGFB3 (MIM * 190,230) and SMAD2 (MIM * 601,366)." (PMID 39008115, 2024). "The fact that neither a panel nor CNV-sequencing (or software equivalent, e.g., ExomeDepth) was used is a significant limitation, since patients with exon deletions or Loeys-Dietz syndrome could have been included in the FBN1 negative group." (PMID 38700693, 2024). "We did not identify any mutations of HTAD genes that cause Loeys-Dietz syndrome, which is associated with early onset TAD and BAV, and a total of three causal mutations in non-syndromic HTAD genes (a glycine substitution in FBN1 and loss of function mutations in SMAD4 and FOXE3)." (PMID 38370698, 2024).